FAM187B (family with sequence similarity 187 member B)
Synonyms: TMEM162; FLJ25660
Tractability: Antibody: UniProt predicts a signal peptide or a membrane-spanning region. PROTAC: ubiquitination databases record sites on it.
Gene: Protein-coding gene on chromosome 19 (35,224,800 to 35,228,739, reverse strand). Ensembl gene ENSG00000177558.
Subcellular location: Membrane
Gene Ontology:
Cellular component: membrane
Genetic constraint (gnomAD): Loss-of-function variants: 22 observed, 24.16 expected, observed/expected ratio (o/e) 0.91, 90% interval 0.65 to 1.3. The upper end of that interval is the gene's LOEUF score, 1.3, which puts it in group 5 of 6, group 1 being the genes least tolerant of losing a copy. Missense variants: 433 observed, 473.05 expected, observed/expected ratio (o/e) 0.92, 90% interval 0.85 to 0.99. Synonymous variants: 192 observed, 205.18 expected, observed/expected ratio (o/e) 0.94, 90% interval 0.83 to 1.05.
Homologues: Orthologues: chimpanzee FAM187B (98% identical), macaque FAM187B (92% identical), dog FAM187B (62% identical), pig FAM187B (60% identical), rabbit FAM187B (54% identical), mouse Fam187b (47% identical), rat Fam187b (46% identical). Paralogues in human: FAM187A (20% identical).